NF1 (neurofibromin 1)
Diseases named in the same sentence as NF1 in open-access papers (continued):
Sharing a sentence is not in itself a finding about the gene and the disease.
gliosarcoma (11 papers, 2019 to 2023). A rare histological variant of glioblastoma (WHO grade IV) characterized by a biphasic tissue pattern with alternating areas displaying glial and mesenchymal differentiation (WHO). "Due to the small number of patients in the two reports, further studies are needed to reveal the overall incidence of NF1 mutations in gliosarcoma." (PMID 34605602, 2021). "We further observed alterations in NF1 in 41% of gliosarcomas via damaging mutations and copy number losses." (PMID 34504233, 2021). "In this patient’s case, acquired mutations in KRAS with oncogenic potential and NF1 with unknown actionability were observed after prolonged exposure to BRAF inhibition along with a morphological transformation to gliosarcoma." (PMID 37231247, 2023). "Gliosarcoma mutations with potential therapeutic indications include BRAF, EGFR, CDKN2A, NF1, and PTEN." (PMID 34504233, 2021). "Somatic coding indels in NF1 (3/10 gliosarcoma samples), PTEN (2/10), RB1 (2/10) and PIK3R1 (2/10) genes with a minimal penetration of 15% (within a given sample) were found in 5/10 samples." (PMID 30818875, 2019). "Our findings demonstrate that gliosarcomas, in terms of somatic alterations, are fairly similar to GBMs, with a higher frequency of NF1 and PTEN alterations, more similar to frequencies observed in mesenchymal GBMs." (PMID 30818875, 2019). "The NF1 gene was altered in 3/10 gliosarcomas due to indels." (PMID 30818875, 2019). "Of the 19 common genes in gliosarcoma, five (BRAF, EGFR, CDKN2A, NF1, and PTEN) were indicated as potentially targetable genes present in the OncoKB database." (PMID 34504233, 2021). "Among the most frequently altered genes found in gliosarcoma, BRAF, EGFR, PTEN, NF1, and CDKN2A are potentially targetable according to OncoKB." (PMID 34504233, 2021). "We demonstrate that most gliosarcoma tumors have somatic alterations of PIK3/Akt (PTEN, PI3K) and RAS/MAPK (NF1, BRAF) signaling pathways that are crucial for tumor growth and therapy resistance." (PMID 30818875, 2019). "Gliosarcomas are similar to primary GBM in their molecular profiles and exhibit a similar rate of NF1, RB1 and PTEN alterations." (PMID 30818875, 2019). "Most gliosarcoma tumors had somatic alterations of PIK3/Akt (PTEN, PI3K) and RAS/MAPK (NF1) signaling pathways that are crucial for tumor growth." (PMID 30818875, 2019). "We demonstrate that gliosarcoma bears somatic alterations in gene coding for PI3K/Akt (PTEN, PI3K) and RAS/MAPK (NF1, BRAF) signaling pathways that are crucial for tumor growth." (PMID 30818875, 2019). "Interestingly, the frequency of PTEN or NF1 alterations was much higher in gliosarcoma than in GBMs, reported to be 41% for PTEN and only 10% for NF1 in GBM patients." (PMID 30818875, 2019).
osteosarcoma (11 papers, 2016 to 2025). A usually aggressive malignant bone-forming mesenchymal neoplasm, predominantly affecting adolescents and young adults. "The variants in NF1 and CDKN2A, found in a patient with MPNST and a patient with osteosarcoma respectively, were detected in the germline, thus confirming the diagnosis of a cancer predisposition syndrome." (PMID 36805510, 2023). "Although osteosarcomas are also rare in patients with NF1, 2 studies have found increased prevalence among these patients." (PMID 33734413, 2021). "However, point mutations or deletions of several tumor suppressor genes, likely to be drivers of osteosarcomagenesis, were observed in a recent report of human osteosarcoma including NF1, NF2 and PTEN, all of which were also recovered in a transposon-based screen for osteosarcoma in mice." (PMID 29056713, 2016). "Of note, 3 samples were assigned to cluster B despite what was expected based on their classifier result: 1 MTT in NF1, that classified as MPNST-like, 1 MPNST in NF1 that classified as osteosarcoma, and 1 MTT in NF1 that classified as RMS-like." (PMID 38178234, 2024).
prostate carcinoma (11 papers, 2013 to 2025). A carcinoma that arises from epithelial cells of the prostate gland. "For example, AR, EGFR, DDR2 and MAP2K2 were connected with mtDNA genes in prostate cancer, and TMPRSS2, NF1, PIK3CA, BRCA1 and TOP1 were the top neighbors of mtDNA genes in multiple cancer types." (PMID 32024997, 2020). "In prostate cancer, LBH589 indirectly inhibits the expression of HMGA2; thus, we wanted to determine whether LBH589 can also inhibit NF1 MPNST cell growth." (PMID 31053152, 2019).
depression (10 papers, 2011 to 2024). "The neurological issues in adult NF1 patients, including learning problems, depression, and dementia, are influenced by gender and Nf1 mutations could participate in the complexity of their pathophysiology." (PMID 38339230, 2024). "These genes included SBNO2, CEACAM5, AKAP1, UBC, ACTB, UBB, and FOS for schizophrenia; SEC24C, PGLYRP1, ARHGAP4, RPL22, SLC6A11, and SYK for bipolar disorder; and SRRT, PARK2, LILRA4, STK17A, IGFBP2, and NF1 for major depression." (PMID 22373040, 2011). "We have also determined whether alterations in hippocampal long-term depression may exist in Nf1 OPG mice, which might help explain their abnormal behavioral responses to novelty." (PMID 23762458, 2013). "Interestingly, the serotonin transporter gene SLC6A4 is susceptible to deletion in NF1 but does not appear to be associated with depression in this population." (PMID 35004058, 2021). "In major depression, APP interacted with the abnormally expressed NF1." (PMID 22373040, 2011).
hepatocellular carcinoma (10 papers, 2017 to 2025). A malignant tumor that arises from hepatocytes.
malignant glioma (10 papers, 2011 to 2024). A grade III or grade IV glioma arising from the central nervous system.
mesenchymal tumors (10 papers, 2014 to 2024). "A pathogenic de novo deletion of the NF1 gene (Ex30-58del, size 285 kb) was found in a second patient with a malignant mesenchymal tumour (PaedCan18)." (PMID 37507557, 2023). "Gastrointestinal stromal tumours (GIST) are rare mesenchymal tumours involving the gastrointestinal tract (GI) associated with NF-1." (PMID 34336521, 2021). "The mesenchymal tumors displayed a significantly lower expression of NF1, in line with the frequent number of mutations in the NF1 tumor suppressor gene reported in the mesenchymal subtype." (PMID 32171051, 2020). "GISTs are predominant mesenchymal tumors observed in individuals with NF-1." (PMID 39403336, 2024).
myeloproliferative disorder (10 papers, 2010 to 2025). A clonal hematopoietic stem cell disorder, characterized by proliferation in the bone marrow of one or more of the myeloid (i.e., granulocytic, erythroid, megakaryocytic, and mast cell) lineages. "NF1 functions as a negative regulator of the RAS signal transduction pathway, cross-talking with the JAK-STAT pathway, and loss of NF1 can lead to a progressive myeloproliferative disorder." (PMID 21646683, 2011). "Loss of NF1 can lead to a progressive myeloproliferative disorder in animal models and in Juvenile myelomonocytic leukemia." (PMID 21339820, 2011). "Mutations in or deletion of Nf1 leads to myeloproliferative disorders." (PMID 20098702, 2010). "The NF1 knockout mice are embryonically lethal, but the transplantation of fetal mouse Nf1−/− cells leads to myeloproliferative disorder in wild-type recipients." (PMID 34768940, 2021). "Studies of human JMML specimens and gene-targeted mice show that NF1 acts as a tumor suppressor in myeloproliferative neoplasms and leukemogenesis by inhibiting Ras signaling." (PMID 24734223, 2014). "In fact, somatic inactivation of NF1 in hematopoietic cells results in a progressive myeloproliferative disorder in mice, with elevated levels of RAS-GTP, although secondary genetic events are required to the development of AML." (PMID 23077663, 2012).
pancreatic cancer (10 papers, 2014 to 2024). "Notably, GSEA analysis of the TCGA pancreatic carcinoma (PDAC) samples demonstrated that NF1 alterations in PDAC were associated with the SASP signature." (PMID 38858602, 2024). "Deregulation of RHOT1 expression may be a risk factor for pancreatic cancer in NF1 microdeletion patients, although the reported data refer to NF1 patients without distinguishing between different forms of NF1." (PMID 38874808, 2024).
skin cancer (10 papers, 2013 to 2026). "Interestingly, a multidisciplinary team at Yale University, led by Yale Cancer Center members, has confirmed that NF1 is a “major player” in the development of skin cancer, which is also observed in this study." (PMID 27930734, 2016). "An 80-year-old female with NF1 presented with a rapidly growing skin tumor of the forehead." (PMID 24137429, 2013).
Stroke (10 papers, 2013 to 2025). Sudden impairment of blood flow to a part of the brain due to occlusion or rupture of an artery to the brain. "This is the first described case of NF1-associated extracranial vertebral artery aneurysm presenting with recurrent embolic stroke." (PMID 28168068, 2017). "In a study, Krishnaswami and Vahidassr reported a 43-year-old young stroke patient with pontine infarct due to vascular ectasia associated with NF1." (PMID 23533858, 2013). "In our report, left middle cerebral arterial occlusion and mutation of heterozygote MTHFR C677T gene accompanied by NF1 were reported to lead to stroke in a 31-year-old woman patient." (PMID 23533858, 2013). "The protective effect of -162 T polymorphism on total stroke and ischemic stroke was also consistent with previous observations which suggested that NF-1, a ubiquitous nuclear factor and a transcriptional activator, has a binding site on PON1 if allele A appears at −162." (PMID 23356507, 2013). "Our case may be the first in literature to determine the coexistence of NF1, the cause of young stroke, and accompanying cerebral artery occlusion and mutation of heterozygote MTHFR C677T gene." (PMID 23533858, 2013). "Therefore, Nf1 leads to an augmented risk of stroke compared to the general population." (PMID 38790247, 2024). "The NF1 cohort presented here, however, was significantly less likely to have suffered a clinical or radiographic stroke prior to presentation." (PMID 38753003, 2024). "In our case, multiple complications rapidly developed in the patient, compounded by a complex medical history that included conditions such as stroke, tuberculosis, pulmonary issues, and NF1." (PMID 39359752, 2024). "As a result, NF1 and heterozygote MTHFR gene mutation were diagnosed in our case with young stroke, and aspirin (300 mg/day) and clopidogrel (75 mg/day) were administered." (PMID 23533858, 2013). "Cases related to vascular abnormalities due to NF1 leading to stroke in young adults are present in literature." (PMID 23533858, 2013). "Because of giving rise to stroke in young adults, vascular abnormalities stemming from NF1 should meticulously be taken into account in such patients." (PMID 23533858, 2013). "Both NF1 patients with (possibly) deleterious RNF213 variants, in whom PCA involvement was also seen, were excluded from further analysis of arterial involvement and strokes." (PMID 37012328, 2023). "In addition, in young patients with the complaint of stroke, MTHFR C677T gene mutation should be considered as etiologic reason, and the mutation should be kept in mind to be accompanied by NF1." (PMID 23533858, 2013).
liposarcoma (9 papers, 2008 to 2025). A usually painless malignant tumor that arises from adipose tissue. "This study also significantly expands the total number of well-differentiated/dedifferentiated liposarcomas and MPNSTs (both NF-1 associated and sporadic) tested and is the first report of staining in a well differentiated liposarcoma." (PMID 27655679, 2016). "NF1, a tumor suppressor gene that negatively regulates Ras signaling, was identified as one of the recurrent deletion genes in dedifferentiated liposarcoma." (PMID 41531533, 2025). "Best responder was decrease of 15% in target lesions in a patient with liposarcoma harboring PIK3CA p.E545K with co-occuring NF1 p.S1420* alteration." (PMID 38126764, 2024). "The NF1 (neurofibromin-1) gene was of particular interest, altered in 13 of 50 well- and de-differentiated liposarcomas." (PMID 27732970, 2017). "LS141 (Liposarcoma) and CHP100 (Ewing Sarcoma) cell lines, on the other hand, have been used extensively and both these cell lines have not been reported to harbor any NF1 mutation/loss (also, personal communication with Kanojia D, Cancer Science Institute, Singapore)." (PMID 29212209, 2017).
meningocele (9 papers, 2014 to 2026). A congenital abnormality in which the meninges protrude through a defect in the spinal column or the cranium. "The thoracic region is the most common site for meningoceles arising in association with NF1, as documented in the medical literature." (PMID 41357572, 2025). "An intrathoracic meningocele is a relatively rare disease, 60 to 85 % of all thoracic meningoceles are associated with neurofibromatosis type I (NF-1)." (PMID 26556010, 2015). "We describe a case with double huge intrathoracic meningoceles associated with NF-1 collaboratively treated with cystoperitoneal (CP) shunt followed by thoracotomic total excision." (PMID 26556010, 2015). "NF1 is associated with intrathoracic meningoceles and vascular fragility." (PMID 42111423, 2026). "Intrathoracic meningocele, although relatively uncommon, is often associated with NF-1." (PMID 38816890, 2024). "Huang and colleagues reported a rare case of NF1-related meningocele, initially misdiagnosed as encapsulated pleural effusion, which led to IHS after thoracentesis." (PMID 41357572, 2025). "Ultimately, 21 articles on surgical treatment for intrathoracic meningocele related to NF-1 were obtained." (PMID 38816890, 2024). "In this article, we present a case of a patient with NF-1 combined with huge intrathoracic meningocele with NF-1 who was misdiagnosed as pleural effusion." (PMID 38816890, 2024). "For NF-1 patients with intrathoracic meningocele, the blind use of thoracoscopy can pose significant risks, including the development of meningitis, pneumocephalus, and even death." (PMID 38816890, 2024). "Literature review comprised 21 patients diagnosed with NF-1 who received surgical intervention for intrathoracic meningocele." (PMID 38816890, 2024). "He had been diagnosed with NF-1 and intrathoracic meningoceles 6 years ago and has been taking conservative treatments." (PMID 32243391, 2020). "Ιmaging revealed a meningocele in the right upper pulmonary area, attributed to her NF-1." (PMID 36348911, 2022). "Dural ectasia, a characteristic finding of NF-1, is an expansion of the thecal sac, which may result in posterior vertebral body scalloping and lateral thoracic meningocele formation." (PMID 25852768, 2014). "In summary, this case highlights the diagnosis and conservative management of an intrathoracic meningocele presenting in adulthood without known NF1." (PMID 39640111, 2024).
multiple endocrine neoplasia (9 papers, 2010 to 2025). Multiple endocrine neoplasia (MEN) is a group of rare inherited cancer syndromes characterized by the development of two or more endocrine gland tumors, sometimes with tumor development in other tissues or organs. "Hereditary PCC and PGL (HPCC/PGL) are usually associated with neoplasm syndromes including multiple endocrine neoplasia (MEN 1 and MEN 2), von Hippel–Lindau (VHL), neurofibromatosis-1 (NF-1), and familial paraganglioma (FPGL)." (PMID 30613466, 2018). "Examples of PPGLA mutations include the RET gene in multiple endocrine neoplasia (MEN) syndromes, the VHL gene in von Hippel–Lindau disease, the NF1 gene in Neurofibromatosis type 1, the MAX gene, or the genes of the succinate dehydrogenase complex (SDHB, SDHD, SDHA, SDHC, SDHAF2)." (PMID 36010170, 2022). "Among 14- and 15-year-olds, a group less likely to be diagnosed with CPS-related cancer, NF1 was detected in three cases overall, HLH in one 14-year-old, and multiple endocrine neoplasia syndrome (MEN) in one 15-year-old, totaling five CPS cases during these two years of life." (PMID 39336731, 2024).
triple-negative breast carcinoma (9 papers, 2016 to 2024). An invasive breast carcinoma which is negative for expression of estrogen receptor (ER), progesterone receptor (PR), and human epidermal growth factor receptor 2 (HER2). "ICB targeting LAG3 and PD-L1 in triple-negative breast cancer (TNBC) mouse models with NF1, TSC1, or TβRII deficient tumors showed significant efficacy." (PMID 38997291, 2024). "ICB targeting LAG3 and PD-L1 simultaneously inhibits metastatic progression in preclinical triple negative breast cancer (TNBC) mouse models of NF1-, TSC1- or TGF-β RII- deficient tumors." (PMID 38997291, 2024). "Previous studies have indicated that NF1 mutations were observed in triple negative breast cancers." (PMID 27245685, 2016). "For this purpose, we used MDA-MB-231 cells, the most commonly used triple-negative breast cancer cell line model, which carry mutations in Ras effector pathway (BRAF and NF1 mutations)." (PMID 38383288, 2024). "PIK3CA and AKT1 mutations were found to be particularly enriched in the luminal B/HER2− subtype, NF1, and ERBB2 mutations were enriched in the luminal B/HER2+ mutation, and PTEN mutations were enriched in triple-negative breast cancer." (PMID 33173047, 2020). "We chose the NF1-/- RASWT MPNST cell line ST8814 and the triple negative breast cancer cell line MDA-MB-231 carrying the oncogenic KRASG13D mutation." (PMID 32163428, 2020).